AFP (alpha fetoprotein)
Diseases named in the same sentence as AFP in open-access papers (continued):
Sharing a sentence is not in itself a finding about the gene and the disease.
sarcopenia (17 papers, 2018 to 2025). Progressive decline in muscle mass due to aging which results in decreased functional capacity of muscles. "Multivariate analysis identified sarcopenia as an independent risk factor for OS (HR: 0.527, p = 0.017), alongside AFP levels and tumor number." (PMID 40308633, 2025). "The prognostic risk grading system based on sarcopenia, AFP ≥ 200 ng/mL, and maximal tumor diameter≥8.9 cm showed significant differences in prognosis between risk groups." (PMID 38434977, 2024). "The prognostic risk grading system based on sarcopenia, AFP, and maximal tumor diameter had good guiding value for the prognosis of patients." (PMID 38434977, 2024). "Univariate analysis showed that albumin, the ALBI grade, AFP, up-to-seven criteria, and preoperative sarcopenia and myosteatosis were associated with OS (all p < 0.05)." (PMID 39456597, 2024). "Based on the results of multivariate analysis of OS and PFS, we constructed a TACE postoperative prognosis risk assessment system based on baseline AFP ≥ 200ng/mL, maximal tumor diameter ≥ 8.9 cm, and sarcopenia." (PMID 38434977, 2024). "The prognosis risk grading system based on sarcopenia, AFP, and maximal tumor diameter had good guiding value for the prognosis of patients." (PMID 38434977, 2024). "Univariable Cox analysis revealed sarcopenia, the satellite nodule status, VI, R1 resection, a relatively large tumor size (>5 cm), multiple tumors, LN involvement, elevated AFP, and CEA as significant risk prognostic factors for OS (p < 0.05)." (PMID 34866356, 2022). "Graft-to-recipient weight ratio, recipient gender, body mass index, alpha-fetoprotein level, tumor size, and microvascular invasion, in addition to sarcopenia, were significantly associated with HCC recurrence (p < 0.05)." (PMID 29740069, 2018). "The results showed that sarcopenia (HR=2.379, 95%CI: 1.552-3.647, P<0.001), AFP ≥ 200 ng/mL (HR=2.083, 95%CI: 1.372-3.161, P=0.001), and maximal tumor diameter (HR=1.153, 95%CI: 1.108-1.199, P<0.001) were independent risk factors for OS." (PMID 38434977, 2024). "Next, we built a nomogram by combining prognostic factors, including age, MELD score, platelet count, AFP, sarcopenia, and more than one complication, and the vertical line from the coordinate axis of each risk index was used to obtain corresponding scores." (PMID 35771410, 2022). "Multiple tumors, maximal tumor diameter ≥ 5cm, major venous thrombosis (VP3 and VP4), sarcopenia, AFP ≥ 200 ng/ml, and albumin<3.5mg/dL were allocated with a score of 1.5, 1.5, 3, 1, 2, and 1, respectively." (PMID 36248997, 2022). "The optimal cut-off value of the AMPAS1 model (age, MELD score, platelet count, alpha-fetoprotein level, sarcopenia, and more than one complication combination) for progression prediction was identified using receiver-operating characteristic (ROC) analysis." (PMID 35771410, 2022). "Next, our scoring system considered both tumor (number, size, AFP, major venous thrombosis), liver (albumin), and patient factors (sarcopenia) at the same time." (PMID 36248997, 2022). "In model 2 of multivariate analysis, ALBI grade 3 (HR: 4.209; 95% CI 2.864–6.186, p < 0.001), presence of pre-sarcopenia, larger tumor size, higher AFP, early PD, and new extrahepatic metastasis, were independent survival predictors." (PMID 33110117, 2020). "AFP >100 mg/dL is a predictor of sarcopenia in HCC patients who are prepared for liver transplantation." (PMID 33247686, 2020). "The power was calculated after adjustment with variance inflation factor (1/0.95) between sarcopenia and two variables (alpha-fetoprotein and microvascular invasion) for the multivariable model expecting the HR 9.4931." (PMID 29740069, 2018). "Time-dependent C-index was graphically greater when the model incorporated sarcopenia with alpha-fetoprotein." (PMID 29740069, 2018).
sarcopenia (continued). "When considering only two preoperative variables (sarcopenia and alpha-fetoprotein), incorporation of sarcopenia with alpha-fetoprotein significantly increased the model fitness (log-likelihood difference = 4.0, p = 0.046)." (PMID 29740069, 2018). "AFP levels in these patients may be confounded by protein-calorie malnutrition, sarcopenia, and chronic systemic inflammation, factors that are common in this population and can reduce marker sensitivity." (PMID 41590616, 2025). "A TACE prognostic grading system was constructed based on whether the patient had AFP ≥ 200 ng/mL, maximal tumor diameter ≥ 8.9 cm, and sarcopenia." (PMID 38434977, 2024). "The results showed that sarcopenia (HR=1.577, 95%CI: 1.181-2.106, P=0.002), AFP ≥ 200 ng/mL (HR=1.361, 95%CI: 1.024-1.809, P=0.033), multifocal tumor (HR=1.423, 95%CI: 1.066-1.899, P=0.017), and maximal tumor diameter (HR=1.075, 95%CI: 1.041-1.110, P<0.001) were independent risk factors for PFS." (PMID 38434977, 2024). "In addition to sarcopenia, our newly proposed scoring system also included factors such as multiple tumors, maximal tumor diameter≥ 5cm, major venous thrombosis, AFP ≥ 200 ng/ml, and albumin<3.5mg/dL." (PMID 36248997, 2022). "Cox regression multivariate analysis demonstrated that sarcopenia, multiple tumors, maximal tumor diameter≥ 5cm, major venous thrombosis, sarcopenia, AFP ≥ 200 ng/ml, and albumin<3.5mg/dL were independent poor prognostic factors for overall survival in HCC patients receiving TACE." (PMID 36248997, 2022). "Moreover, the degree of model fitness was significantly better when the model includes sarcopenia in addition to alpha-fetoprotein and microvascular invasion than when the model only include alpha-fetoprotein and microvascular invasion (log-likelihood difference = 4.6, p = 0.032)." (PMID 29740069, 2018). "Using Cox univariate analysis, the following variables were significantly associated with 540-day survival: age, albumin levels, presence of sarcopenia, CTP score, MELD score, AFP levels, PROSASH-II groups, and ECOG-PS." (PMID 38539416, 2024). "In conclusion, sarcopenia had excellent predictive value for the OS and PFS of post-TACE patients, and AFP ≥ 200ng/mL and maximal tumor diameter were also independent risk factors for poor prognosis." (PMID 38434977, 2024). "However, multivariate analysis identified only sarcopenia, more than one complication, age, MELD score, platelet < 100 × 109/L, and AFP < 6.2 mmol/L as independent predictors of progression." (PMID 35771410, 2022). "Older age [odd ratio (OR): 310.19; p = 0.007]; Child-Pugh classification B or C (OR: 15.24; p = 0.047); higher AFP (OR: 128.49; p = 0.008); higher PIVKA-II (OR: 118.54; p = 0.027); and larger PTV (OR: 51.31; p = 0.026) were significant factors for newly developed sarcopenia after RT." (PMID 31681607, 2019). "Overall, mean age, MELD score, lymphocyte count, NLR, TBIL, INR, CRP, IL-6, proportion of sarcopenia, and more than one complication were higher in the patients who experienced progression; conversely, the mean L3 SMI, platelet count, ALT, sodium, and AFP were lower (p < 0.05)." (PMID 35771410, 2022). "These 20 patients were significantly older, higher Child-Pugh classification B or C, higher level of AFP and PIVKA-II, and larger PTV than in patients who still had no sarcopenia after RT." (PMID 31681607, 2019).
ataxia telangiectasia (16 papers, 2009 to 2026). Ataxia-telangiectasia is the association of severe combined immunodeficiency (affecting mainly the humoral immune response) with progressive cerebellar ataxia. "The twin brother also had the same pathogenic variants, T and B cell lymphopenia, and elevated AFP level confirming the diagnosis of ataxia-telangiectasia." (PMID 34539671, 2021). "When accompanied by an IgA deficiency, finding a complex underlying primary immunodeficiency, such as ataxia telangiectasia, should be considered and a serum alpha-fetoprotein measurement as well as a lymphocyte phenotyping and oriented karyotyping can be achieved." (PMID 27642394, 2016). "Additional unusual physiochemical properties are observed in individuals with ataxia- telangiectasia, such as high levels of plasma alpha-fetoprotein and an increased sensitivity to ionising radiation." (PMID 34197485, 2021). "In patient 3, alpha-fetoprotein was measured due to the presence of cerebellar telangiectasia and was found at the upper limit of normal, although no additional clinical or laboratory features supported a diagnosis of ataxia–telangiectasia." (PMID 41496005, 2026). "Genetic workup included normal fluorescent in situ hybridization for chromosome 22q11.2 deletion and normal alpha-fetoprotein that ruled out DiGeorge syndrome and ataxia telangiectasia, respectively." (PMID 40028343, 2025). "Literature showed that high levels of AFP in children with suspected chronic ataxia, along with a profile of low levels of IgA, IgE, and IgG and a low lymphocyte count (CD4+ and CD8+), is suggestive of and supports an early diagnosis of Ataxia telangiectasia." (PMID 36267884, 2022). "Serum AFP levels may also be increased in conditions that do not affect the liver, such as ataxia telangiectasia and Finnish-type nephrotic syndrome." (PMID 35455589, 2022). "In addition, AFP can be expressed in other malignancies, of which HCC is the most frequent, and some non-tumor diseases, such as Fanconi anemia and ataxia-telangiectasia." (PMID 31836006, 2019).
Cerebellar atrophy (16 papers, 2008 to 2025). Cerebellar atrophy is defined as a cerebellum with initially normal structures, in a posterior fossa with normal size, which displays enlarged fissures (interfolial spaces) in comparison to the foliae secondary to loss of tissue. "We identified a novel SETX homozygous c.5308_5311delGAGA mutation that co-segregates with ARCA with cerebellar atrophy and raised AFP." (PMID 18405395, 2008). "A combination of said clinical symptoms, laboratory findings (elevated alpha-fetoprotein and reduced immunoglobulin levels), and radiological findings (cerebellar atrophy) are key to differentiating A-T from other conditions." (PMID 40564629, 2025). "Five patients had mainly clinical presentations including unsteady gait, dysarthria, bulbar conjunctive telangiectasia, cerebellar atrophy, intellectual disability, stunted growth, increase of alpha-fetoprotein in serum, lymphopenia." (PMID 35586824, 2022). "Although, a few unique clinical features differentiate each of these forms, the patients also share common clinical signs, such as the presence of cerebellar atrophy, sensorimotor axonal neuropathy, and elevated alpha-fetoprotein (AFP) serum level." (PMID 23941260, 2013). "We report that AOA1, AOA2 and AT which together should be considered as a particular group among ARCAs, share many features including complex, overlapping oculomotor disturbances, elevated AFP along with sensorimotor axonal neuropathy, chorea and/or dystonia, cerebellar atrophy and severity." (PMID 29127364, 2017). "The autosomal recessively inherited ataxia with oculomotor apraxia 2 (AOA2) is a neurodegenerative disorder characterized by juvenile or adolescent age of onset, gait ataxia, cerebellar atrophy, axonal sensorimotor neuropathy, oculomotor apraxia, and elevated serum AFP levels." (PMID 19744353, 2009). "Moreover, elevated serum alpha-fetoprotein (AFP) and apparent cerebellar atrophy were observed." (PMID 27644330, 2016).
Germ Cell Cancer (16 papers, 2012 to 2026). "The levels of LDH, AFP and hCG are factors for the risk stratification of TC based on the International Germ-Cell Cancer Collaborative Group classification." (PMID 31652641, 2019). "Elevated CA-125 and AFP correlated well with epithelial and malignant germ cell tumors, respectively." (PMID 42073127, 2026). "Patients with malignant germ cell tumor often have higher serum levels of alpha-fetoprotein (AFP) and human chorionic gonadotropin (HCG)." (PMID 38398164, 2024). "The International Germ Cell Cancer Collaborative Group (IGCCCG) classification has identified an AFP level >10,000 ng/mL as one of the factors determining poor prognosis." (PMID 38001671, 2023). "Serum AFP levels are essential for the diagnosis of malignant germ cell tumors, especially ESTs." (PMID 36207682, 2022). "Metastatic involvement and high levels of human beta-choriogonadotropin (bHCG) 23,594 IU/L and alpha-fetoprotein (AFP) 2159 mIU/L classified the patient into the intermediate prognostic group based on the International Germ Cell Cancer Collaborative Group classification." (PMID 31200669, 2019). "There was a clear correlation between AFP and malignant germ cell tumor." (PMID 22410253, 2012). "Although patients with a malignant germ cell tumor often have higher levels of AFP and HCG, those clinical features with high specificity were not selected by LASSO, which may in part be due to few patients having a malignant germ cell tumor in the study population." (PMID 38398164, 2024). "The serum biomarkers AFP, β-HCG and LDH play an important role in the diagnosis and prognosis of TGCTs, and they are included in the prognostic index of the International Germ Cell Cancer Consensus Group." (PMID 38067334, 2023). "According to the International Germ Cell Cancer Collaborative Group (IGCCCG) criteria, the patient was stratified as having poor prognosis due to the presence of non-pulmonary visceral metastases and markedly elevated tumor markers, including AFP and beta-HCG." (PMID 39727674, 2024). "In addition, the evaluation of serum tumor markers (AFP, beta-hCG, LDH) is required for the correct diagnosis and classification of EGCTs according to the International Germ Cell Cancer Collaborative Group (IGCCCG)." (PMID 35554637, 2022). "Biochemical tumor markers, such as alpha-fetoprotein (AFP), beta-human chorionic gonadotropin (hCG), and lactate dehydrogenase (LDH), serve as standard adjuncts in diagnosis and are incorporated into staging systems like the International Germ Cell Cancer Collaborative Group (IGCCCG) classification." (PMID 41283275, 2025).
liver failure (16 papers, 2014 to 2026). A liver disease characterized by the liver losing or has lost all of its function. "The results showed that the AFP score, which focuses solely on tumor-related factors, performs the worst, reflecting its inability to capture the competing risk of liver failure." (PMID 41536859, 2026). "Conversely, Alpha-fetoprotein (AFP) score focuses on tumor progression but overlooks the competing risk of liver failure." (PMID 41536859, 2026). "Previous studies have identified an association between several factors, including age, AFP, and platelets, and poor outcomes related to liver failure, which is consistent with our study." (PMID 35771410, 2022). "Cluster 5 presents low albumin and serum sodium, accompanied by low AFP, suggesting a transitional stage of liver failure." (PMID 41536859, 2026). "At present, the clinical value of alpha-fetoprotein (AFP) in the prognosis of liver failure has attracted great attention." (PMID 36769497, 2023). "The main complications of resection include hepatic failure and recurrence; therefore, surveillance should be performed every 3 to 6 months by imaging and serum alpha-fetoprotein (AFP) measurements." (PMID 38001637, 2023). "Regarding liver regeneration in liver failure, previous studies have shown that the expression of AFP can appear in the early stage of liver regeneration after partial liver resection." (PMID 36769497, 2023). "Recently, TAL deficiency was also reported in a 13‐month‐old male with mild liver failure and elevated AFP levels upon exposure to APAP, which were responsive to treatment with NAC." (PMID 31769880, 2020). "In clinical practice, serum alpha-fetoprotein (AFP) is usually used as a predictive biomarker for monitoring the prognosis of patients with liver failure because it reflects the regeneration of hepatocytes in response to liver injury." (PMID 24829587, 2014). "So far, only 10 patients with PFIC5 from six unrelated families have been reported, usually presenting as rapidly progressive liver failure, vitamin K independent coagulopathy, high alpha-fetoprotein (AFP) and ultimately required a liver transplant (LT) to save lives." (PMID 38641832, 2024). "Some studies have shown that AFP is a prognostic and protective factor for liver failure, but AFP is closely related to tumors, and is mostly used as a positive marker of liver tumors, so it is for tumor patients or patients who cannot be ruled out., The application of AFP may be controversial." (PMID 34612778, 2021). "Kakisaka et al29 suggested that serum AFP level may reflect the induction of liver progenitor cells in acute liver failure patients, and the persistent induction of liver progenitor cells may be needed for a recovery from liver failure." (PMID 31769901, 2020). "Intrasplenic or injection of SC-derived hepatocytes to human or animal with liver injury or liver failure increased ALB, AFP, CK-19, and antitripcin mRNA expression, ALB secretion, serum ALB concentration, and reduced bilirubinemia." (PMID 36685673, 2023). "For patients with HBV-ACLF where AFP levels are elevated by less than fivefold, including non-cirrhotic Type A or B liver failure patients, we found that the 60-day survival rate is less than 10%." (PMID 38245594, 2024).